OR5D18 (olfactory receptor family 5 subfamily D member 18)
Description:
Odorant receptor.
Synonyms: OR11-143
Tractability: Antibody: UniProt places it where antibodies can reach, with medium confidence; UniProt predicts a signal peptide or a membrane-spanning region; its Gene Ontology location is reachable by antibodies, with medium confidence.
Gene: Protein-coding gene on chromosome 11 (55,819,630 to 55,820,571, forward strand). Ensembl gene ENSG00000186119.
Subcellular location: Cell membrane
Pathways (Reactome):
Sensory Perception: Expression and translocation of olfactory receptors
Gene Ontology:
Molecular function: olfactory receptor activity; G protein-coupled receptor activity
Biological process: G protein-coupled receptor signaling pathway; sensory perception of smell; detection of chemical stimulus involved in sensory perception of smell
Cellular component: plasma membrane; membrane
Genetic constraint (gnomAD): Loss-of-function variants: 0 observed, 0.38 expected, observed/expected ratio (o/e) 0, 90% interval 0 to 1.85. That is too few expected variants to judge how well the gene tolerates losing a copy. Missense variants: 392 observed, 379.5 expected, observed/expected ratio (o/e) 1.03, 90% interval 0.95 to 1.12. Synonymous variants: 157 observed, 155.87 expected, observed/expected ratio (o/e) 1.01, 90% interval 0.88 to 1.15.
Homologues: Orthologues: chimpanzee OR5D18 (98% identical), dog OR5D18 (85% identical), mouse Or5d18 (82% identical), rat Or5d18 (82% identical), mouse Or5d47 (75% identical), rat Or5d47 (75% identical), mouse Or5d35 (75% identical), rat Or5d35 (74% identical), pig OR5D18 (73% identical). Paralogues in human: OR5D16 (81% identical), OR5D14 (71% identical), OR5D3 (67% identical), OR5D13 (64% identical), OR5L1 (62% identical), OR5L2 (61% identical), OR5I1 (55% identical), OR5J2 (54% identical), OR8U3 (54% identical), OR8D1 (54% identical), OR5B21 (53% identical), OR5AP2 (53% identical), and 84 more.